CD14 (CD14 molecule)
Diseases named in the same sentence as CD14 in open-access papers (continued):
Sharing a sentence is not in itself a finding about the gene and the disease.
kidney disease (9 papers, 2014 to 2024). "Overexpression of Tab2 is associated with the leaky-gut molecule (soluble CD14) and also plays a key role in kidney disease via translocation of uremic toxins such as p-cresyl and indoxyl that promote CKD." (PMID 38814931, 2024). "Several studies show that mature and/or activated CD14+CD16++ blood monocytes are associated to progression of renal disease." (PMID 32850849, 2020). "We stained a unique set of bouin-fixed paraffin-embedded kidney biopsies from 37 patients with acute HFRS and 43 patients with other kidney diseases (controls) for HLA-DR, CD14, CD16 and CD68." (PMID 33690725, 2021). "Studies have found that the number of circulating CD14 monocytes in patients with kidney disease is significantly reduced." (PMID 34735495, 2021). "The initial values of CD14+CD16+ monocytes before the kidney transplantation were higher as compared to values in healthy subjects reflecting the end stage kidney disease." (PMID 24499053, 2014). "Analysis using STITCH predicted that host proteome changes may lead to leaking of the gut, allowing molecules such as soluble CD14 and p-cresol to pass through to promote kidney disease." (PMID 38814931, 2024). "The frequency of HLA-DR+, CD14+, CD16+ and CD68+ cells were all significantly increased in patients with HFRS as compared to patients with other kidney diseases." (PMID 33690725, 2021). "Compared to diabetic patients without kidney disease, diabetic patients with kidney disease had a substantial increase in the number of total MDSCs and a rise in the percentage of CD14- cells." (PMID 39290701, 2024). "In addition, immunosenescence seems to be more pronounced in patients with kidney diseases than in healthy controls, as shown by severe chronic inflammation, accumulation of immune cells with the senescent phenotype (CD28− T cells, CD14+CD16+ monocytes), and proinflammatory cytokine production." (PMID 36384564, 2022).
adenocarcinoma (7 papers, 2011 to 2024). A common cancer characterized by the presence of malignant glandular cells. "Moreover, we found a significantly lower proportion of CD14++/CD16+ intermediate monocytes in patients with adenocarcinoma before the operation, which are commonly defined as a proinflammatory monocyte subset." (PMID 37610509, 2023). "Previously, our group assessed the levels of toll-like receptor 4 (TLR4), its co-receptor CD14, and the NF-κB p65 subunit to investigate the role of β-carotene in inhibiting the lipopolysaccharide (LPS)/TLR4 signaling pathway in human adenocarcinoma colon epithelial (HT-29) cells." (PMID 39588046, 2024). "We have confirmed this in our studies; using flow cytometry we demonstrated that the A549 adenocarcinoma cells line does not express CD14." (PMID 21789185, 2011).
kidney (7 papers, 2006 to 2025). "Mechanistically, the activation of Dectin-1 led to the downregulation of TLR4 and its co-receptor CD14, thereby, undermining the TLR4 signaling in hepatic stellate cells and inhibiting liver fibrosis and oncogenesis." (PMID 39590166, 2024). "CD14, IL-1beta, and TNF were upregulated early in the kidney but decreased by day 8 to 12 pi which coincided with infiltration of inflammatory cells into the kidney and possible acute kidney injury or tubular injury (indicated by the white arrows)." (PMID 34265022, 2021).
heart disease (5 papers, 2012 to 2025). "Furthermore, because monocytes participate in atherosclerotic lesion progression and CD14+ CD16+ intermediate monocytes are associated with heart disease, these AD-associated changes are clinically relevant (116, –, 118)." (PMID 41294355, 2025). "As monocytes increased in chagasic and non-chagasic individuals with heart disease, we determined the frequency of classical, intermediate, and non-classical monocytes according to CD14 and CD16 expression." (PMID 31379862, 2019).
neurological diseases (4 papers, 2009 to 2023). "Surface expression of TLR4 and CD14 in microglia has been shown to be elevated in various neurological disorders like ALS and AD." (PMID 23234315, 2012). "Finally, our findings focus on cognition and HIV; however, it is likely these findings will extend beyond HIV and contribute to other neurological diseases and disorders because CD14+CD16+ monocytes have emerged as a principal driving cell type for a number of proinflammatory conditions." (PMID 33914710, 2021).
psychiatric disorder (4 papers, 2019 to 2023). A disorder characterized by behavioral and/or psychological abnormalities, often accompanied by physical symptoms. "The first model (Model-1), including butyric acid, LBP/CD14, and in addition age, testosterone, cortisol, healthy food servings, and psychiatric disorders, explained 47% of BMI variability (adjusted R2 = 0.47)." (PMID 31491976, 2019). "MSEA analysis of the A.1 and B.1 branches show an enrichment of miRNAs expressed in CD14+, CD15+, CD19+, CD3+, and CD56+ immune cell types, which are known markers of neuroinflammation and have been increasingly implicated in neurodegenerative and psychiatric disorders." (PMID 35392269, 2022).
liver (3 papers, 2022 to 2025). "Higher levels of TGF-β and lower levels of IL-1β, CD14, and CCR5, markers of circulating neutrophils, suggest that TOLLIP deficiency may facilitate the resolution of chronic inflammation during colon carcinogenesis." (PMID 36499030, 2022).
inflammatory myopathies (2 papers, 2025). "As expected, macrophage markers (CD14 and CD68) were upregulated at higher levels than in other inflammatory myopathies." (PMID 40568658, 2025). "Macrophage markers (CD14, CD68) were also upregulated, at levels similar to those seen in other inflammatory myopathies." (PMID 41441888, 2025).
benign tumors (1 paper, 2020). "The data obtained by Silverberg show that PD-L1 expression on monocytes and CD14+ cells in PB was significantly higher at the early stage (FIGO I) of OC in comparison to benign tumors." (PMID 33062717, 2020).
neurodevelopmental disorder (1 paper, 2022). A behavioral and cognitive disorder with onset during the developmental period that involves impaired or aberrant development of intellectual, motor, or social functions. "This study also compared CD14+ monocyte differential gene expression to published gene lists for DEGs in the brains of individuals with psychiatric and neurodevelopmental disorders, and ASD risk genes published by the Simons Foundation." (PMID 36688057, 2022).
vasculopathy (1 paper, 2025). "Notably, mice deficient in platelet TGFβ1 show less MPA and CD14+CD16+ monocytes, along with reduced inflammation and vasculopathy." (PMID 39665236, 2025).
CD14 also shares sentences with these, for which no sentence is quoted: acute myocardial infarction (11 papers); chronic periodontitis (8); abdominal aortic aneurysm (4); macrophage activation syndrome (4); rheumatic diseases (4); unstable angina (4); Aicardi-Goutières Syndrome (3); Brain atrophy (3); gastritis (3); Hodgkins lymphoma (3); acute cholangitis (2); apical periodontitis (2); Arthralgia (2); asbestosis (2); Breast Invasive Ductal Carcinoma (2); carcinoma in situ (2); chronic heart failure (2); chronic hepatitis (2); chronic hepatitis B (2); chronic liver failure (2); coagulopathies (2); colon adenocarcinoma (2); colon polyp (2); dilated cardiomyopathy (2); enterocolitis (2); erythroleukemia (2); fracture (2); Glucose intolerance (2); head and neck cancer (2); heart transplant (2).
A further 171 diseases each share a sentence with CD14 in 2 papers or fewer.